ALKBH5 (alkB homolog 5, RNA demethylase)
Diseases named in the same sentence as ALKBH5 in open-access papers (continued):
Sharing a sentence is not in itself a finding about the gene and the disease.
breast cancer (continued). "ALKBH5 also promotes a breast cancer phenotype; under hypoxic conditions, ALKBH5 expression increases, thus decreasing levels of m6A and upregulating expression of the pluripotency factor NANOG." (PMID 29061143, 2017). "Knockdown of ALKBH5 expression in MDA-MB-231 human breast cancer cells significantly reduced their capacity for tumor initiation as a result of reduced numbers of breast cancer stem cells (BCSCs)." (PMID 29125541, 2017). "In breast cancer cells, hypoxia leads to upregulation of ALKBH5, which then results in decreased m6A levels." (PMID 28533023, 2017). "Upregulation of ALKBH5 also induced the loss of m6A in NANOG mRNA, which in turn increased its stability and NANOG protein levels in breast cancer stem cells (BCSCs)." (PMID 28533023, 2017). "We have also analyzed the effect of ALKBH5 or ZNF217 loss of function on the BCSC phenotype and breast cancer metastasis." (PMID 27590511, 2016). "Immunohistochemical analysis revealed that HIF-1α and ALKBH5 expression were highly correlated in human breast cancer biopsies, suggesting that the data from in vitro and in vivo analysis of breast cancer cell lines are clinically relevant." (PMID 27590511, 2016). "Although hypoxia induced the BCSC phenotype in all breast-cancer cell lines analyzed, it did so through variable induction of pluripotency factors and ALKBH5 or ZNF217." (PMID 27590511, 2016). "We performed immunohistochemistry on sections from 9 representative breast cancer biopsies to analyze ALKBH5 and HIF-1α expression." (PMID 27590511, 2016). "Immunohistochemistry revealed that expression of HIF-1α and ALKBH5 was concordant in all human breast cancer biopsies analyzed." (PMID 27590511, 2016). "ALKBH5 knockdown in MDA-MB-231 breast cancer cells significantly decreased metastasis from breast to lungs in immunodeficient mice." (PMID 27590511, 2016). "Under hypoxia, the expression of ALKBH5 in breast cancer cells was up-regulated by hypoxia-inducible factor, which resulted in a decrease in the m6A modification level of NANOG mRNA, which in turn increased the NANOG protein level and promoted the enrichment of breast cancer stem cells." (PMID 40356909, 2025). "Interestingly, ALKBH5 knockdown in a breast cancer cell line decreased metastasis from breast to lung in vivo." (PMID 37369946, 2023). "Therefore, inhibiting the ALKBH5/GLUT4 axis is of great significance in improving the efficacy of HER2 targeted therapy for breast cancer, including trastuzumab and lapatinib." (PMID 37582735, 2023). "In response to hypoxia, hypoxia-inducible factor (HIF)-1α and HIF-2α were stimulated to promote ALKBH5 expression in breast cancer cells; subsequently, ALKBH5 inhibited the m6A level in the 3′UTR of Nanog mRNA and increased NANOG expression, resulting in enhanced breast cancer stem cell phenotype." (PMID 35859892, 2022). "According to previous studies in the literature, it was found that HIF contains two key factors, HIF-1α and HIF-2α, which can activate the transcriptional expression of m6A demethylase ALKBH5 gene at the transcriptional level in the development of breast cancer." (PMID 35733918, 2022). "Therefore, ALKBH5-mediated m6A modifications play a pivotal role in maintaining breast cancer stemness in the hypoxic environment." (PMID 35859892, 2022). "Conversely, ALKBH5 knockdown in human breast cancer cells suppressed tumor initiation capacity." (PMID 35859892, 2022). "Additionally, ALKBH5 decreases breast cancer sensitivity to doxorubicin by removing the m6A methylation of BRCA1 for mRNA stabilization and increases DNA repair competency." (PMID 36551544, 2022). "ALKBH5 was higher in breast cancer tissue than in adjacent normal tissue of TNBC." (PMID 35721510, 2022).
breast cancer (continued). "Overexpression of the m6A reader YTHDF3 or the m6A demethylase ALKBH5 may enhance the transcription of m6A-enriched genes in breast cancer, facilitating breast cancer brain metastasis." (PMID 34976022, 2021). "In addition, ALKBH5, as an oncogene, regulates the self-renewal and proliferation of breast cancer tumour stem cells." (PMID 34044876, 2021). "The expression of HIF-1α and ALKBH5 were consistent in human breast cancer biopsies analyzed." (PMID 34745269, 2021). "ALKBH5 has been reported to be dysregulated with either tumor-promoting or tumor-inhibiting roles in various cancer types, including pancreatic cancer, lung cancer, breast cancer and HCC." (PMID 34112124, 2021). "Demethylases (FTO and ALKBH5) and methyltransferases (such as Metl3 and Metl14) have been reported to regulate the progression of several types of cancers, including liver, lung, and breast cancers 49-52." (PMID 34512165, 2021). "Hypoxia enhances breast cancer by ALKBH5-mediated and HIF-dependent Nanog mRNA m6A-demethylation." (PMID 35004266, 2021). "ALKBH5, another member of the AlkB family, is highly expressed in most breast cancers." (PMID 34044876, 2021). "Moreover, knockdown of ALKBH5 expression significantly inhibits tumour formation and decreases breast cancer stem cell number in breast tumours." (PMID 34044876, 2021). "In addition, it is confirmed that ALKBH5 was also up-regulated in breast carcinoma, promoted demethylation of m6A, and then improved the stemness of breast cancer cells." (PMID 33363011, 2020). "In breast cancer, ALKBH5 expression is induced upon hypoxia in a HIF-dependent manner." (PMID 32111216, 2020). "For example, the overexpression of YTHDF1 is related to poor prognosis in patients with liver cancer; downregulation of ALKBH5 in MDA-MB-231 human breast cancer cells can lead to a decrease in the number of breast cancer stem cells, resulting in a significant reduction in tumorigenic capacity." (PMID 32596399, 2020). "Moreover, the number of breast cancer ctem cells can be reduced by ALKBH5 knockdown in breast cancer." (PMID 32742465, 2020). "In breast cancer, hypoxia elevated the expression of ALKBH5, and then, demethylated NANOG mRNA." (PMID 30987661, 2019). "Overexpression of ALKBH5 could increase the frequency of the breast cancer (BC) stem-cell phenotype by m6A-mediated demethylation of NANOG gene." (PMID 30953473, 2019). "In addition to its role in GBM, ALKBH5 expression is reported to be induced by hypoxia in breast cancer cells." (PMID 29125541, 2017). "We previously reported that exposure of breast cancer cells to hypoxia induces the ALKBH5-mediated demethylation of N6-methyladenosine (m6A) in NANOG mRNA leading to increased expression of NANOG, which is a pluripotency factor that promotes BCSC specification." (PMID 27590511, 2016). "However, in every breast cancer line, the hypoxic induction of pluripotency factor and ALKBH5 or ZNF217 expression was HIF-dependent." (PMID 27590511, 2016). "Additionally, ALKBH5 was upregulated by approximately 2.5-fold (p < 0.01) in breast cancer cells." (PMID 38665783, 2024). "Since the HIPPO pathway is an essential component controlling stem cell self-renewal, and ALKBH5 has been suggested to promote the enrichment of breast cancer stem cells, we inferred that ALKBH5 might influence MM stem cell (MMSC) maintenance, proliferation, and survival." (PMID 35414790, 2022). "In breast cancer, downregulation of ALKBH5 and m6A may drive cancer stem cell formation." (PMID 34307344, 2021). "In addition, ALKBH5 overexpression decreased the percentage of breast cancer stem cells." (PMID 34044876, 2021). "Moreover, elevation of ALKBH5 increases the expression of NANOG in breast cancer stem cells." (PMID 30062093, 2018). "Notably, ALKBH5 was required for acquisition of the breast cancer stem cell phenotype." (PMID 28081722, 2017).
breast cancer (continued). "In breast cancer, the expression levels of METTL14 and ALKBH5 regulate each other and together promote tumour development by regulating m6A modification levels in specific transcripts associated with epithelial-mesenchymal transition (EMT) and angiogenesis." (PMID 40356909, 2025). "Under hypoxia, which is a common phenomenon of solid tumors, ALKBH5-mediated demethylation stabilizes NANOG transcripts, reactivating their function in the self-renewal trajectory and maintenance of the breast cancer stem cell (BCSC) pool." (PMID 41157107, 2025). "ALKBH5 enhances cancer cell proliferation, reverses DNA damage, and inhibits apoptosis, leading to reduced ADR sensitivity, as observed in breast cancer." (PMID 39465506, 2025). "In breast cancer, hypoxia-inducible factor 1α (HIF1α) and HIF-2α stimulate the expression of ALKBH5 which can demethylate NANOG mRNA and increase its stability, inducing the breast cancer stem cell (BCSC) phenotype." (PMID 40483535, 2025). "In contrast, the increased expression of ALKBH5 promoted m6A demethylation and the stability of GLUT4 mRNA in a YTHDF2-dependent manner, which resulted in enhanced glycolysis in drug-resistant breast cancer cells." (PMID 40001461, 2025). "The m6A demethylase ALKBH5 is a direct target of HIF-1α and HIF-2α and is hypoxic regulated in a variety of cell lines, including breast cancer and adipocytes." (PMID 38227578, 2024). "ALKBH5‐dependent approach induces increased NANOG mRNA and protein expression and breast cancer stem cell phenotype." (PMID 39006762, 2024). "Mechanistic research has revealed that ALKBH5 targets GLUT4, ensuring its mRNA stability and facilitating glycolysis in breast cancer cells." (PMID 37055798, 2023). "A recent study revealed that hypoxia tumor microenvironment increased ALKBH5 expression, which eliminated m6A modified NANOG and enhanced its mRNA stability, thereby promoted breast cancer stem cell phenotype 46." (PMID 37283789, 2023). "Additionally, other m6A regulators, YTHDF1 and ALKBH5, were also engaged in chemoresistance (including adriamycin, cisplatin, and olaparib) by enhancing DNA damage repair in breast cancer (BC)." (PMID 36517820, 2022). "Consistent with our findings, ALKBH5 has been reported to positively regulate Nanog stability and expression in response to hypoxia-inducible factor (HIF)-1α and HIF-2α in breast cancer stem cells (BCSCs)." (PMID 35552718, 2022). "For example, m6A modification mediated by the cooperation of METTL14, ALKBH5, and YTHDF3 was reported to influence the cell cycle, induce the progression of EMT, and contribute to angiogenesis of cancer cells in breast cancer." (PMID 34996459, 2022). "In breast cancer, ALKBH5 expression is induced in a HIF-dependent manner and overexpression of ALKBH5 reduces m6A modification and stabilizes Nanog mRNA, contributing to breast cancer stem cell formation." (PMID 35399719, 2022). "Several members (e.g., METTL3, METTL14, FTO, ALKBH5, and YTHDF2) actively participate in human cancers such as acute myeloid leukemia, glioblastoma, breast cancer, and endometrial cancer." (PMID 34363020, 2021). "This study suggests that m6A demethylase ALKBH5 and m6A methyltransferase inhibitor ZNF217 have important effects on BCSC phenotype and breast cancer metastasis." (PMID 34745269, 2021). "For example, hypoxia can alter the level/activity of METTL14, ALKBH5, and YTHDF3, leading to decreased m6A modification in the target transcripts in breast cancer cells." (PMID 34094986, 2021). "ALKBH5 overexpression induced by HIF1A reduces the methylation of NANOG mRNA, leading to increased expression of NANOG and breast cancer stem cells." (PMID 33430133, 2021).
breast cancer (continued). "Elevated levels of ALKBH5 demethylate the transcripts of pluripotency-related gene Nanog homeobox (NANOG) thereby increasing its expression, and inducing breast cancer stem cell phenotype." (PMID 34484567, 2021). "Recent researches noted that ALKBH5 up-regulated the expression of NANOG by demethylating m6A and promoted the gathering of breast cancer cells in the tumor microenvironment." (PMID 32742194, 2020). "In breast cancer, the tumor-promoting activity of the m6A regulators such as METTL3 and ALKBH5 were also described." (PMID 33584787, 2020). "Overexpression of ALKBH5 reduces m6A modification and stabilizes NANOG mRNA, thereby contributing to breast cancer stem cell formation." (PMID 32111216, 2020). "It was reported that hypoxia induces the breast cancer stem cell phenotype by HIF-dependent and ALKBH5-mediated m6A-demethylation of NANOG mRNA." (PMID 33489865, 2020). "Aberrant expression of m6A regulators, including METTL3, METTL14, WTAP, ALKBH5, and FTO, has been identified in breast cancer, as well as their potential prognostic values." (PMID 33585234, 2020). "In GSE70905, YTHDC1 (p < 0.05), IGFBP1 (p < 0.001), ALKBH5 (p < 0.001), WTAP (p < 0.001), YTHDF3 (p < 0.001) and HNRNPA2B1 (p < 0.001) were down-regulated in breast cancer to the adjacent." (PMID 33362863, 2020). "In breast cancer, ALKBH5 mediated the m6A-demethylation of NANOG mRNA, thereby inducing the breast cancer stem cell phenotype." (PMID 30987661, 2019). "In their study, they showed that ALKBH5 increased NANOG expression level by demethylating NANOG mRNA in the 3’UTR, promoting breast cancer stem cell renewal." (PMID 30922314, 2019). "Recently, it was reported that a HIF-regulated decrease in m6A through an increase in ALKBH5 and/or ZNF217 expression maintains pluripotency of breast cancer stem cells in several established breast cancer cell lines." (PMID 30131850, 2018). "Similar to hypoxia exposure, overexpression of ALKBH5 not only decreases NANOG mRNA methylation, but also increases NANOG (Nanog homeobox) levels, resulting in elevation of the CSC population in breast cancer." (PMID 29439529, 2018). "The same group showed further that both ALKBH5 and ZNF217 participate in the hypoxia-induced NANOG and KLF4 (another pluripotency factor gene) overexpression in breast cancer cells." (PMID 29686311, 2018). "The hypoxic induction of pluripotency factor, ALKBH5 and ZNF217 expression depends on HIF, meaning that HIF is vital for breast cancer therapy." (PMID 30062093, 2018). "In several breast cancer cell lines, hypoxia induced the HIF-dependent expression of AlkB homolog 5 (ALKBH5), which is an enzyme that removes N6-methyl groups from adenosine residues in RNA." (PMID 27590511, 2016). "We previously demonstrated that hypoxia-induced m6A demethylation of NANOG mRNA by ALKBH5 positively regulated NANOG expression and the BCSC phenotype in MCF-7 and MDA-MB-231 breast cancer cells." (PMID 27590511, 2016). "Following doxorubicin treatment of breast cancer cells, PRMT5 induces nuclear translocation of the RNA demethylase ALKBH5, which removes m6A methylation from BRCA1 mRNA, stabilizing the transcript and enhancing DNA repair capacity to ultimately attenuate doxorubicin efficacy." (PMID 40919714, 2025). "Notably, the m6A demethylases FTO and ALKBH5 have been reported to be functionally essential in a variety of tumors such as AML and breast cancer." (PMID 40435251, 2025). "However, the contribution of ALKBH5 to invasive breast cancer (BC) remains poorly understood." (PMID 39127986, 2024). "The abundance of RBM15 and ALKBH5 in lung cancer cell lines exhibited a negative correlation with those in breast cancer cell lines." (PMID 38665783, 2024). "In breast cancer, ALKBH5 expression is induced by hypoxia‐inducible factor 1α (HIF1α) and HIF1β, and its overexpression under hypoxic conditions reduces NANOG mRNA methylation levels, increasing the number of breast cancer stem cells." (PMID 39445003, 2024).
breast cancer (continued). "The ablation of METTL3 caused apoptosis and reduced the invasiveness of lung adenocarcinoma cells, whereas hypoxia-activated m6A demethylase ALKBH5 induces the accumulation of breast cancer stem cells through HIF-dependent and ALKBH5-mediated m6A demethylation of NANOG mRNA." (PMID 37391814, 2023). "Specifically, ALKBH5 removes the m6A modification of GLUT4 mRNA in cancer cells, and recruits YTHDF2 to combine with GLUT4 mRNA to enhance its stability, leading to increased glycolysis of breast cancer cells and resistance to HER2 targeted therapy." (PMID 37582735, 2023). "Strikingly, WTAP and the eraser FTO were downregulated in breast cancer cell lines compared to normal epithelial cells, whilst no changes were observed for ALKBH5." (PMID 36725888, 2023). "On the one hand, breast cancer stem cell (BCSC) phenotype could be induced by hypoxia through HIF-dependent and ALKBH5-mediated regulation of NANOG mRNA." (PMID 35444654, 2022). "Considering ALKBH5’s functions in cancer stem cell maintenance in breast cancer, GBM, AML and endometrial cancer, ALKBH5 could be a potential target for suppressing cancer stem cells and promoting complete remission in cancer treatment." (PMID 35063010, 2022). "Previous studies reported that ALKBH5 could up-regulate NANOG expression via regulating the demethylation of NANOG in different tumors, like breast cancer, oral squamous cell carcinoma and ovarian cancer." (PMID 33975615, 2021). "Under hypoxic conditions, HIF-1α and HIF-2α induces ALKBH5 expression, which leads to enhanced mRNA stability of pluripotency factor genes such as NANOG and promotes the self-renewal and proliferation of breast cancer stem cells by increasing the stability of NANOG mRNA110." (PMID 33741974, 2021). "Additionally, ALKBH5 and ZNF217 were found to regulate a breast cancer stem cell (BCSC) phenotype in hypoxia, resulting in decreased m6A methylation of NANOG and KLF4 and increased expression of these pluripotency factors." (PMID 33669361, 2021). "ALKBH5 suppresses NANOG and KLF4 degradation, which promotes breast cancer progression." (PMID 32021563, 2020). "In breast cancer, Zhang and colleagues proposed that the exposure of breast cancer cells to hypoxia could stimulate hypoxia-inducible factor (HIF)-1α- and HIF-2α-dependent expression of ALKBH5, which induced m6A demethylation and stabilization of NANOG mRNA." (PMID 29587823, 2018). "Using this model of breast cancer development, we found that immortalization resulted in reduced m6A levels as well as significant down-regulation of the m6A methylation complex (METTL3/14) and up-regulation of the primary demethylase (ALKBH5)." (PMID 30131850, 2018). "We next analyzed the expression of ALKBH5 and HIF-1α in human breast cancer biopsies." (PMID 27590511, 2016). "Indeed, ALKBH5 overexpression decreases m6A methylation of NANOG mRNA at 3′ untranslated region (3′UTR), increasing NANOG mRNA stability and levels, and induces BCSC enrichment in hypoxic breast cancer cells." (PMID 35063010, 2022). "In addition, ALKBH5, as the second m6A demethylated enzyme discovered after FTO, was reported to promote tumor stem formation in gliomas and promote tumor progression in breast cancer, colon cancer and hepatocellular carcinoma." (PMID 36347025, 2022). "Thalhammer and colleagues identified that the ALKBH5 promoter contains two putative binding sites for HIF-1α and was up-regulated in response to hypoxia across several different cancer cell lines, including U2OS, breast cancer cell line MCF7, and neuroblastoma cell line IMR32." (PMID 33669361, 2021). "ALKBH5 demethylates m6A marks from NANOG, a master pluripotency factor; the oxidative demethylation activity of the ALKBH5 increases the NANOG transcript and protein expression that enriches breast cancer stem cells in the reduced oxygen tumor microenvironment promoting cancer progression." (PMID 33511112, 2020).